MASP2 (MBL associated serine protease 2)
Diseases named in the same sentence as MASP2 in open-access papers (continued):
Sharing a sentence is not in itself a finding about the gene and the disease.
ovarian carcinoma (3 papers, 2014 to 2020). A malignant neoplasm originating from the surface ovarian epithelium. "Moreover, MASP-2 is significantly associated with recurrence and poor survival of colorectal as well as ovarian cancers, thus suggesting a link with poor RFS, similar to data found in this study." (PMID 32961854, 2020). "It is concluded that the expression of MBL and MASP-2 is altered in ovarian cancer, possibly indicating involvement of the lectin pathway of complement activation in the disease." (PMID 25038892, 2014). "The local expression of MBL2 and MASP2 genes was higher in women with ovarian cancer compared with controls." (PMID 25038892, 2014). "Neither MASP-2 serum concentration nor the +359 A>G polymorphism of its gene was associated with ovarian cancer." (PMID 25038892, 2014).
pneumococcal infection (3 papers, 2012 to 2017). Infections with bacteria of the species streptococcus pneumoniae. "Previous studies in pneumococcal infection showed increased disease severity among Masp2-deficient and MASP-2 antibody-treated mice, which was mainly driven by decreased opsonization of bacteria, leading to increased bacterial counts in the peripheral blood." (PMID 28086930, 2017). "This was confirmed by a study in Masp2-deficient mice that showed increased susceptibility to intranasal pneumococcal infection due to decreased opsonization of S. pneumoniae." (PMID 28086930, 2017). "Here we report that MASP-2 deficient mice (which can still activate complement via the classical pathway and the alternative pathway) are highly susceptible to pneumococcal infection and fail to opsonize Streptococcus pneumoniae in the none-immune host." (PMID 22792067, 2012). "Hence, MBL deficient mice are not compromised in pneumococcal infection, while ficolin A deficient mice and mice deficient of the key lectin pathway enzyme MBL-associated serine protease-2 (MASP-2) are exquisitely susceptible to infection." (PMID 22792067, 2012).
type 1 diabetes (3 papers, 2016 to 2023). "Furthermore, the differences in F2 and HGFAC, together with associations related to MASP2 and SERPING1, suggest the hypercoagulative state previously reported in type 1 diabetes." (PMID 37537394, 2023).
acute lymphoblastic leukaemia (2 papers, 2018). "Similar results of increased MASP-2 serum levels were described in children with tumors of the central nervous system and in patients with acute lymphoblastic leukemia and non-Hodgkin's lymphoma." (PMID 30532757, 2018).
angioedema (2 papers, 2013 to 2021). Swelling involving the deep dermis, subcutaneous, or submucosal tissues, representing localized edema. "Since C1INH controls several systems that influence bradykinin formation, any factor that contributes to an increase in bradykinin formation, such as activation of the contact system or MASP-1 or MASP-2, could cause an attack of angioedema." (PMID 24013493, 2013). "Important to realize for HAE-C1INH patients is that both the activity of MASP-1 and MASP-2 are controlled by C1INH and MASP-1 and MASP-2 levels are elevated during episodes of stress and infection, known initiators of angioedema episodes." (PMID 24013493, 2013). "We found a significant increase in MASP-2 levels in the 1/3 of patients during angioedema attacks, which supports the notion that MASP-2 may contribute to edema formation." (PMID 33725263, 2021).
cardiomyopathy (2 papers, 2014 to 2019). A disease of the heart muscle or myocardium proper. "Considering the biological relevance between collectin-11 and MASP2 and that MASP2 genetic variants were associated with high risk of cardiomyopathy in chronic CD, the genetic interaction between COLEC11 and MASP2 variants were analyzed." (PMID 30995222, 2019). "The concomitant presence of these genetic variants and MASP2 risk mutations greatly increased the odds for cardiomyopathy." (PMID 30995222, 2019). "COLEC11 and MASP2*CD risk genotypes were associated with cardiomyopathy (p = 0.014; OR 9.3, 95% CI 1.2–74) and with the cardiodigestive form of CD (p = 0.005; OR 15.2, 95% CI 1.7–137), suggesting that both loci act synergistically in immune modulation of the disease." (PMID 30995222, 2019). "The frequency of the risk genotypes in both loci (COLEC11 AG+GG and MASP2*CD+ carriers) was higher in patients with cardiodigestive form (21%) and cardiomyopathy (13%), than healthy controls (2%), (p = 0.005, OR 15.2, 95% CI 1.7–137; p = 0.014, OR 9.3, 95% CI 1.2–74, respectively)." (PMID 30995222, 2019). "Genetic variants and protein levels of MASP-2 and the mannose-binding lectin (MBL), a molecule structurally similar to collectin-11, have been found to be associated with susceptibility to T. cruzi infection and clinical progression to cardiomyopathy." (PMID 30995222, 2019).
Cerebral ischemia (2 papers, 2016 to 2019). Restriction of arterial blood supply to the brain associated with insufficient oxygenation to support the metabolic requirements of the tissue. "Absence of LP activity in MASP-2 gene-targeted mice and in WT mice treated with MASP-2 inhibitors confers significant protection from ischemia/reperfusion injury in mouse models of myocardial, intestinal and cerebral ischemia." (PMID 31608060, 2019). "This work demonstrates the essential role of the low-abundant MASP-2 in the mediation of cerebral ischemia-reperfusion injury and demonstrates that targeting MASP-2 by an inhibitory therapeutic antibody markedly improved the neurological and histopathological outcome after focal cerebral ischemia." (PMID 27577570, 2016).
cervical intraepithelial neoplasia (2 papers, 2018 to 2022). "In this investigation, we determined the serum levels of MASP-1, MASP-2, MASP-3, MAp-44, and MAp-19 in patients with cervical cancer and cervical intraepithelial neoplasia (CIN)." (PMID 30532757, 2018).
chronic kidney disease (2 papers, 2021 to 2025). Impairment of the renal function secondary to chronic kidney damage persisting for three or more months. "Importantly, intrarenal complement gene expression (C1R, C1QB, C6, C9, C5, MASP2) predicts nonresponse to induction therapy, alluding to the potential pathogenic role of intrarenal complement gene expression in chronic kidney disease." (PMID 41031884, 2025).
coronary artery disease (2 papers, 2018 to 2025). "Conversely, patients with coronary artery disease showed a positive correlation between plasma MASP-2 and MAp44 levels, indicating a compensatory mechanism played by MAp44 to inhibit myocardial damage." (PMID 41155225, 2025). "MASP-2 levels determined within two days after admission were almost 50% lower compared with healthy individuals or patients with stable coronary artery disease (CAD)." (PMID 29910807, 2018).
diabetes (2 papers, 2021 to 2024). "Both human and animal studies determined that plasma levels of C3, C4, C4b, iC3b, MBL, MASP-2, C5b-9 Factor B, and Bb were found to be significantly increased in diabetes condition and have a role in exacerbating the pathophysiology of diabetes mellitus." (PMID 38564496, 2024). "In prediabetes, type 1 and type 2 DM, plasma levels of MBL, MASP-1 and MASP-2 are elevated, and animal models have shown that MASP-1 levels rise just before the onset of DM symptoms." (PMID 33729332, 2021).
diabetic nephropathy (2 papers, 2019 to 2020). "Other potential biomarkers for diabetic nephropathy include miR-21-5p, miR-15b, miR-34a, miR-636, MASP2, CALB1, myeloblastin, elafin, cystatin B, and neutrophil gelatinase-associated lipocalin, all of which increase in the presence of the condition." (PMID 32849923, 2020).
glomerular disease (2 papers, 2019 to 2026). "Recent advances in complement-targeted therapies—including inhibitors of C3, C5, factor B, and MASP-2—are entering glomerular disease trials, with early evidence of efficacy in proteinuria reduction and slowing of glomerular injury." (PMID 41792651, 2026).
hereditary angioedema (2 papers, 2019 to 2020). Hereditary angioedema (HAE) is a genetic disease characterized by the occurrence of transitory and recurrent subcutaneous and/or submucosal edemas resulting in swelling and/or abdominal pain. "With experimental evidence of a role for the LP in atherogenesis, MASP-2 inhibitors that are currently being evaluated for hereditary angioedema and other disorders, could also be considered to intervene in the platelet-complement crosstalk driving atherogenesis." (PMID 31555668, 2019).
ischemic stroke (2 papers, 2020 to 2024). A stroke disorder caused by obstruction of blood flow to the brain, due to thrombotic (local blood clot formation) or embolic (due to a blood clot or other material traveling from another site) event. "In an experimental model of ischemic stroke, we reported that combined deficiency of MASP-1 and MASP-3 did not affect the ischemic outcome, while that of MASP-2 was protective." (PMID 33115535, 2020).
malaria (2 papers, 2012 to 2013). Malaria is a serious and sometimes fatal disease caused by a parasite that commonly infects a certain type of mosquito which feeds on humans. "MASP2 inhibitors need to be studied as potential adjunctive therapy for the various manifestations of malaria." (PMID 22380611, 2012). "As MBL forms an active complex with MASP2, the potential interaction between the MBL2 and MASP2 genotypes was also analysed, to evaluate whether specific allele combinations of the two could render the individual susceptible to malaria." (PMID 22380611, 2012).
renal fibrosis (2 papers, 2019 to 2023). A final common manifestation of a wide variety of chronic kidney diseases characterized by glomerulosclerosis and tubulointerstitial fibrosis. "Amongst these, TGFβ1 plays a key role in the development of renal fibrosis and was reduced at the protein level in both MASP-2−/− and HG4 treated mice with proteinuria." (PMID 31608060, 2019).
SARS-CoV infection (2 papers, 2009 to 2018). "As the downstream protein of MBL, variants of the MASP2 gene may be associated with SARS-CoV infection." (PMID 19405982, 2009).
Sepsis (2 papers, 2020 to 2021). Sepsis is defined as life-threatening organ dysfunction caused by a dysregulated host response to infection. "However, whether severe inflammation drives increased H-ficolin, MASP-2 and MAp19 levels or pre-existing protein concentrations predispose individuals to severe sepsis is unclear." (PMID 33995410, 2021).
subarachnoid haemorrhage (2 papers, 2020 to 2024). "Elevated MASP-2 brain levels were associated with increased TBI severity, as identified by altered pupillary reactivity and the presence of subarachnoid hemorrhage." (PMID 38807149, 2024).
type 2 diabetes mellitus (2 papers, 2019 to 2022). A type of diabetes mellitus that is characterized by insulin resistance or desensitization and increased blood glucose levels. "In type 2 diabetes mellitus (T2DM) rats, the expression of MASP2, a key factor to activate the lectin pathway, is upregulated in renal tubular cells." (PMID 35924242, 2022).
acute-on-chronic liver failure (1 paper, 2020). Acute-on-chronic liver failure (ACLF) is an extreme condition during the natural history of chronic HBV infection, with a relatively high short-term mortality. "Interestingly, in HBV-chronically infected patients that undergo acute-on-chronic liver failure, MASP-1 production was found repressed, whereas MASP-2 was up-regulated—being both mostly produced in the liver." (PMID 33643280, 2020).
autoimmune hepatitis (1 paper, 2022). Hepatitis caused by autoantibodies. "The association of circulating MASP-2 and factor H with the clinical features of patients with autoimmune hepatitis (AIH) is unclear." (PMID 35677590, 2022).
bacteremia (1 paper, 2018). "It should however be stressed that relatively high incidence of MASP2 +359 A/G heterozygosity was noted among LYMPH patients who experienced bacteremia while relatively low - of +1111 A/C heterozygosity in LYMPH group in general." (PMID 30294330, 2018).
bacterial meningitis (1 paper, 2017). Inflammation of the membranes surrounding the brain and spinal cord due to a bacterial infection. "MASP-2 levels in cerebrospinal fluid of patients with bacterial meningitis were correlated with poor functional outcome." (PMID 28086930, 2017).
bladder cancer (1 paper, 2023). "In addition, mannan-binding lectin serine protease (MASP2), a serum protease that plays an important role in the activation of the complement system via mannose-binding lectin, was downregulated in the sEV fractions of the bladder cancer patients." (PMID 37371512, 2023). "Meanwhile, the most interesting proteins downregulated in the samples of bladder cancer patients were: collagen alpha-1 (VI) chain (COL6A1), fructose biphosphate aldolase B (ALDOB) and mannan-binding lectin serine protease (MASP2)." (PMID 37371512, 2023). "Based on these ROC curves, LASPGFPGEYANDQERR3 (=MASP2), TFISPIK2 (=C3), VTAAPQSVCALR2 (=A2M), KTPEELLR2 (=CHMP2A) and SVDPDSPAEASGLR2 (=NHE-RF1) have a high discriminating power between the bladder cancer patients and the healthy control group and might be good biomarker candidates." (PMID 37371512, 2023).
C. perfringens infection (1 paper, 2025). "Moreover, the findings underscore a coordinated effort of the host to mitigate the C. perfringens infection via activating immune (a.o., C3, CFH, MASP2, MBL2) and acute phase (CP, ORM, TF, ExFAB) related proteins." (PMID 40275387, 2025).
cervical cancer (1 paper, 2018). A primary or metastatic malignant neoplasm involving the cervix. "In conclusion, our study shows that high MASP-2, MASP-1, and MAp-19 serum levels are associated with cervical cancer progression and worse disease prognosis." (PMID 30532757, 2018). "Corroborating these observations, in our study high MASP-2 serum concentrations were related to worse prognosis in cervical cancer and interestingly, they were mainly altered in patients who died and/or had disease recurrence." (PMID 30532757, 2018). "ROC curve was used to show the sensitivity and specificity for MASP-2 serum concentrations in relation to the prognosis of cervical cancer progression." (PMID 30532757, 2018). "Our study demonstrates that MASP-2, MASP-1, and MAp-19 could have a role in the progression of cervical cancer." (PMID 30532757, 2018).
Cirrhosis (1 paper, 2022). A chronic disorder of the liver in which liver tissue becomes scarred and is partially replaced by regenerative nodules and fibrotic tissue resulting in loss of liver function. "Low serum levels of MASP-2 in patients with cirrhosis in this study may be associated with decreased hepatic protein synthesis due to liver dysfunction." (PMID 35677590, 2022). "Serum levels of MASP-2 in patients with CHC (921 ng/ml, p = 0.021) or cirrhosis (656 ng/ml, p <0.001) were lower than those in HCs." (PMID 35677590, 2022). "We measured serum MASP-2 and factor H levels in patients with liver diseases other than AIH, such as CHC, DILI, and cirrhosis without AIH." (PMID 35677590, 2022).
cognitive deficits (1 paper, 2024). "In aggregate, the study demonstrated that inhibition of MASP-2, but not of MASP-1, improved the cognitive deficits in the TBI mice with a modest protection of the sensorimotor functions." (PMID 38807149, 2024).
colon cancer (1 paper, 2013). "Similarly, elevated MBL and MASP-2 concentrations and activities were found in patients with colon cancer." (PMID 23744477, 2013).
congenital heart disease (1 paper, 2019). A heart disease that is present at birth. "Here we report an investigation of pre-operative serum MASP-1, MASP-2, MASP-3, MAp44, MAp19 and ficolin-3, concentrations and their possible influence on the incidence of post-operative complications in infants and children operated on because of congenital heart disease." (PMID 30814659, 2019).
crescentic glomerulonephritis (1 paper, 2016). A histopathologic term for a pattern of diseases characterized by extensive crescent formation in the glomeruli; patients present clinically with rapid deterioration of renal function, and possible progression to end-stage renal failure within weeks or months. "Therefore, a plausible explanation for the increase in crescentic glomerulonephritis seen in MASP‐2‐deficient mice is their tendency to enhanced fibrin generation." (PMID 27235854, 2016). "We confirmed that MBL (and hence MASP‐2) is deposited in the glomeruli of mice with crescentic glomerulonephritis, due to anti‐MPO IgG as this would be a requirement for an effect on glomerular fibrin formation." (PMID 27235854, 2016). "We first induced crescentic glomerulonephritis in mice by injecting anti‐MPO antibody and compared disease severity at day 7 in MASP‐2‐deficient mice with wild types." (PMID 27235854, 2016). "Overall, these data demonstrated that MASP‐2‐deficient mice are not protected from crescentic glomerulonephritis induced by anti‐MPO antibodies and are in fact predisposed to more severe disease." (PMID 27235854, 2016).
diffuse large B-cell lymphoma (1 paper, 2020). "The variant allele associated with MASP2 gene polymorphism at position +1111 (rs1271152) seemed to be protective against diffuse large B-cell lymphoma (DLBCL)." (PMID 32635486, 2020).
esophageal SCC (1 paper, 2020). "Previous studies have found an association between MASP-2 expression and cancer; MASP-2 expression significantly correlates with late clinical stage and nodal metastasis, thus indicating its role in cancer progression and aggressive tumor behavior in esophageal SCC." (PMID 32961854, 2020).
focal segmental glomerulosclerosis (1 paper, 2012). A renal disorder characterized by sclerotic lesions in the glomeruli. "MASP2 is a serum protease that activates the complement cascade, which regulates the maintenance of glomerular permeability and the pathogenesis of focal segmental glomerulosclerosis." (PMID 22536212, 2012).
gout (1 paper, 2020). A condition characterized by painful swelling of the joints, which is caused by deposition of urate crystals. "Then, a validation cohort demonstrated the serum levels of MASP2 in SLE, showing with significantly higher expression as compared to that in RA, gout, OA, SS, AS patients." (PMID 32677764, 2020).
hypertension (1 paper, 2022). The presence of chronic increased pressure in the systemic arterial system. "The urinary excretion of MASP-2 in normal urine samples and its association with uEVs from healthy control persons and essential hypertensive patients was independently confirmed by proteomic analyses." (PMID 36153401, 2022).
infarction (1 paper, 2019). A localised pathological necrosis of tissue resulting from obstruction of the blood supply usually by a thrombus, an embolus, or vascular torsion. "In mice, genetic MASP-2 deficiency or pretreatment with MASP-2–inhibitory mAbs was shown to result in smaller infarction size in myocardial and gastrointestinal IR injury models and to reduce neurological deficit and histopathological lesion after focal cerebral ischemia." (PMID 30952698, 2019).
Insulin resistance (1 paper, 2023). Increased resistance towards insulin, that is, diminished effectiveness of insulin in reducing blood glucose levels. "High MASP-2 contributes to hyperactivation of the complement cascade that may promote adipose tissue inflammation and insulin resistance via stimulation of macrophage infiltration and M1 polarization." (PMID 37941903, 2023).
ischemia reperfusion injuries (1 paper, 2020). "Thus, liver-targeted inhibition of MASP-2 might be beneficial clinically to treat many ischemia reperfusion injuries (IRI) due to their dependency on MASP-2." (PMID 32153567, 2020).
liver dysfunction (1 paper, 2022). "Because MASP-2 is mainly produced in the liver, decreased circulating MASP-2 levels in patients with AIH may be associated with decreased hepatic protein synthesis due to liver dysfunction." (PMID 35677590, 2022).